APOBEC3A (apolipoprotein B mRNA editing enzyme catalytic subunit 3A)
Diseases named in the same sentence as APOBEC3A in open-access papers (continued):
Sharing a sentence is not in itself a finding about the gene and the disease.
infection (19 papers, 2011 to 2025). The state of being infected such as from the introduction of a foreign agent such as serum, vaccine, antigenic substance or organism. "At the later cytopathic stages of infection, paracrine type I/III interferon signaling mediated local APOBEC3A/B mutagenesis in uninfected bystander cells “witnessing” infection in the viral extrusion microenvironment." (PMID 41337590, 2025). "To investigate the function of Apobec3A during HAdV infection, we used the V5-Apobec3A inducible HepaRG-TR-Apobec3A cell line, in which the stable expression of V5-Apobec3A is induced with Tet, and we investigated key viral markers for productive infection." (PMID 37154747, 2023). "This indicates that rather than destabilizing this cellular protein, both viral proteins are required, and the interplay between E1B-55K and E4orf6 together are necessary to increase Apobec3A levels during infection." (PMID 37154747, 2023). "The V5 Apobec3A signal intensities were calculated in a bar chart, confirming the significant upregulation at 48 and the continued stabilization at 72 h post wt infection." (PMID 37154747, 2023). "The band intensities in the Western blots were calculated and normalized in the lower chart, thereby confirming Apobec3A protein stabilization during infection." (PMID 37154747, 2023). "Other factors related to the persistence of the infection are the APOBEC3A proteins, which act as antiviral protection mechanisms through epigenetic mechanisms." (PMID 37397749, 2023). "BKPyV-infection led to significantly elevated APOBEC3A and APOBEC3B protein, increased deaminase activity and greater numbers of apurinic/apyrimidinic sites in the host urothelial genome." (PMID 35194151, 2022). "APOBEC3A transcript was increased by BKPyV-infection in some donors (Donors 6 & 7 showed > 2-fold induction), but this trend was not replicated in all." (PMID 35194151, 2022). "Further studies using a hairpin YTCA probe, designed to favour APOBEC3A-deamination, also showed increased activity following BKPyV-infection." (PMID 35194151, 2022). "Furthermore, a qPCR analysis of E1A, E4orf6, and Hexon mRNA showed that Apobec3A expression also strongly downregulates viral transcripts during infection." (PMID 37154747, 2023). "The antiviral effect of APOBEC3A is exerted at viral DNA accumulation during de novo infection through a mechanism that may involve deamination." (PMID 21966267, 2011). "In these cells, APOBEC3A affects the amount of vDNA synthesized over the course of infection." (PMID 21966267, 2011). "The susceptibility to the antiviral effect of APOBEC3A is conserved among primate lentiviruses, although the viral protein Vpx coded by members of the SIVSM/HIV-2 lineage provides partial protection from APOBEC3A during infection." (PMID 21966267, 2011). "Our results indicate that APOBEC3A is a previously unrecognized antiviral factor that targets primate lentiviruses specifically in myeloid cells and that acts during the early phases of infection directly in target cells." (PMID 21966267, 2011). "A growing body of evidence suggests that the host enzyme APOBEC3A plays a significant role in shaping MPXV evolution by introducing characteristic mutations that may drive viral diversification and adaptation during human infection." (PMID 41277969, 2025). "Recent evidence indicates that the host enzyme APOBEC3A, which is highly expressed in human skin cells, may contribute to the evolution of MPXV by introducing characteristic mutations such as GA > AA and TC > TT during infection." (PMID 41277969, 2025). "Importantly, the calculation revealed that despite the siRNA treatment against Apobe3A, the HAdV infection chiefly overruled the knockdown of Apobec3A; however, the mean Apobec3A mRNA levels were decreased by approximately half, compared to the control siRNA during infection." (PMID 37154747, 2023).
infection (continued). "Among the APOBEC protein family members, APOBEC3A and APOBEC3B are able to restrict the infection of multiple viruses, including parvovirus, hepatitis B virus (HBV), human papillomavirus, human immunodeficiency virus 1 (HIV-1) and carcinogenesis." (PMID 37903974, 2023). "Our infection studies with HAdV mutant viruses show that the E1B-55K/E4orf6 E3 ubiquitin ligase does not target Apobec3A for proteasomal degradation to eliminate this novel host restriction factor." (PMID 37154747, 2023). "No significant change was observed with the expression of ADAR1–3, APOBEC1, APOBEC2, and APOBEC3A 3D, 3G, and 3H, whereas APOBEC3B, and 3C had a significant decrease, and APOBEC3F had a significant increase in A549 cells during the course of infection with H7N9." (PMID 29363430, 2018). "Finally, it is worth mentioning here that APOBEC3A has been found to inhibit infection of myeloid cells by alpharetroviruses, and by lentiviruses, such as HIV-1 and SIVmac/HIV-2; and that Vpx compromised the stability of APOBEC3A." (PMID 21994799, 2011). "Importantly, nearly 90% of all SNPs exhibited APOBEC3-like mutation signatures (TC > TT and GA > AA), consistent with editing by the host enzyme APOBEC3A, a process increasingly recognized as a key driver of MPXV evolution and diversification during human infection." (PMID 41277969, 2025). "However, because APOBEC3A/B enzymes were not induced during initial infection of urothelial tissue or organ cultures by BKPyV, it is implausible that APOBEC3A/B induction was a response to early infection or virion exposure of bystander cells." (PMID 41337590, 2025). "Moreover, we found that APOBEC3A and APOBEC3G used different mechanisms to block infection in vivo." (PMID 24851906, 2014). "Interestingly, our preliminary data futher suggest that APOBEC3A levels are upregulated when SAMHD1 is depleted, raising the possibility of a cooperation between the two restriction factors to counteract the infection (data not shown)." (PMID 23497353, 2013).
adenocarcinoma (2 papers, 2023 to 2025). A common cancer characterized by the presence of malignant glandular cells. "We also observed strong correlations between APOBEC3A and GRHL3 expression (Fig. EV2D), and GRHL3 activity scores (Fig. EV2E) in bulk RNA-seq data from SCCs, and from adenocarcinomas of the cervix (CESC-AD) and oesophagus (ESCA-AD)." (PMID 39548236, 2025).
cardiovascular disease (2 papers, 2015 to 2023). "Those SNPs identified as potential APOBEC3A/G-mediated RNA editing sites were disproportionately associated with cardiovascular diseases, digestive system diseases, and musculoskeletal diseases." (PMID 37577456, 2023).
blood cancers (1 paper, 2019). "A potential association of AID and APOBEC3A in a certain type of blood cancers is another interesting outcome of our study." (PMID 30759888, 2019).
metabolic disease (1 paper, 2022). A congenital disorder (due to inherited enzyme abnormality) or acquired (due to failure of a metabolically important organ) disorder resulting from an abnormal metabolic process. "Overall, elevated APOBEC3A copies may lead to increased cholesterol and fatty acid biosynthesis and decreased catabolism, which increases the risks of various metabolic diseases." (PMID 35651912, 2022). "Of note, we found that APOBEC3A expression was also increased in patients with non-alcoholic steatohepatitis (NASH), especially in NASH in combination with fibrosis (unpublished data), suggesting that APOBEC3A may play a role in other metabolic diseases as well." (PMID 35651912, 2022).
APOBEC3A also shares sentences with these, for which no sentence is quoted: head and neck squamous cell carcinoma (4 papers); breast tumors (2); diffuse large B-cell lymphoma (2); Human Papillomavirus Infection (2); lung squamous cell carcinoma (2); lymphoid neoplasm (2); pancreatic ductal adenocarcinoma (2); prostate adenocarcinoma (2); prostate carcinoma (2); skin cancer (2); acute lymphoblastic leukemia (1); AIDS (1); Alzheimer disease (1); bile duct cancer (1); biliary tract cancer (1); cerebral infarction (1); cervical squamous cell carcinoma (1); cholangitis (1); Cholecystitis (1); chronic lymphocytic leukemia (1); chronic myelogenous leukemia (1); colorectal tumors (1); digestive system diseases (1); endocervical adenocarcinoma (1); esophageal cancer (1); gallstones (1); hepatitis B virus infection (1); lupus (1); lymph node metastasis (1); musculoskeletal diseases (1).
A further 5 diseases each share a sentence with APOBEC3A in 1 paper.